CHST15 (carbohydrate sulfotransferase 15)
Diseases named in the same sentence as CHST15 in open-access papers:
CHST15 is named in the same sentence as 36 diseases in open-access papers, as found by Europe PMC text mining. Sharing a sentence is not in itself a finding about the gene and the disease. The quoted sentences say what the papers report.
pancreatic cancer (8 papers, 2015 to 2023). "In contrast, the overexpression of another sulfotransferase, Chst15, is associated with tumor growth in pancreatic cancer." (PMID 34169071, 2021). "The existing literature suggests that CHST15 exerts oncogenic effects in pancreatic cancer stroma, esophageal cancer, breast cancer, and ovarian cancer." (PMID 34922539, 2021). "A promising clinical trial with carbohydrate sulfotransferase 15 (CHST15)-siRNA (STNM01) for patients with pancreatic cancer was completed in Japan." (PMID 31284594, 2019). "CHST15 mRNA is highly expressed in the human pancreatic cancer cell lines PANC-1, MIA PaCa-2, Capan-1 and Capan-2." (PMID 26642349, 2015). "We first confirmed the abundant expression of CHST15 mRNA in the pancreatic cancer cell lines PANC-1, MIA PaCa-2, Capan-1 and Capan-2 using RT-PCR." (PMID 26642349, 2015). "In order to demonstrate the efficacy of CHST15 siRNA, the pancreatic tumors in the nude mice were analyzed by HE staining and CHST15 immunohistochemical staining." (PMID 26642349, 2015). "In summary, our study demonstrated that RNAi-mediated down-regulation of CHST15 effectively inhibits the proliferation and growth of pancreatic tumor cells." (PMID 26642349, 2015). "A similar study showed that CHST15 expression could be detected in the pancreatic cancer cells cytoplasm and fibroblasts in the cancer stroma." (PMID 37545696, 2023). "Mutations of CHST3 gene cause skeletal dysplasia, chondrodysplasia, and autosomal recessive multiple joint dislocations while increased tissue expression of CHST11, CHST12 and CHST15 is an unfavourable prognostic factor in ovarian cancer, glioblastoma and pancreatic cancer, respectively." (PMID 37545696, 2023). "More importantly, Chst15 siRNA has been tested in a Phase 1 Clinical trial for Crohn’s disease patients with active mucosal lesions, and a Phase I/IIa trial for patients with pancreatic cancer, and has a good safety profile." (PMID 35604022, 2022). "CHST15 was also critical for the prognosis in breast cancer and pancreatic cancer." (PMID 34966741, 2021). "Although the study was unable to show which cell types were CHST15 positive, it provided insight into the possible SULT application as target for pancreatic cancer treatment." (PMID 37545696, 2023). "Increased tissue expressions of CHST11, CHST12 and CHST15 were shown to be unfavourable prognostic factors of ovarian cancer, GBM and pancreatic cancer, respectively." (PMID 37545696, 2023). "In addition, overexpression of CHST15 may account for the prognosis of pancreatic cancer, invasive activity of breast cancer cells and enhanced proliferation and sensitization to apoptosis of esophageal squamous cell carcinoma cells, suggesting the possibility that CHST15 is a functional oncogene." (PMID 35798703, 2022). "We focused on the effect of CHST15 directly on tumor, but not stromal, cell proliferation, a primary step of tumor progression, in the human pancreatic cancer cell line PANC-1." (PMID 26642349, 2015).
breast cancer (7 papers, 2016 to 2022). A primary or metastatic malignant neoplasm involving the breast. "As mentioned in Introduction, CS is modified by sulfation by multiple sulfotransferases, including CHST11 and CHST15, which are involved in the synthesis of E units and are upregulated in breast cancer cells." (PMID 35712490, 2022). "Of these sulfotransferases, it has been reported that the expression of CHST11 and CHST15 is upregulated in breast cancer cells." (PMID 35712490, 2022). "Although CHST15 has been described in the literature as being oncogenic in some cancers, including in breast cancer, its regulation by the ERK pathway or by HOX transcription factors has not been described." (PMID 34445617, 2021). "Little evidence exists for the roles of CHST15 and NPIPB11 in genetic predisposition in familial breast cancer." (PMID 28076423, 2017).
melanoma (4 papers, 2017 to 2025). A malignant, usually aggressive tumor composed of atypical, neoplastic melanocytes. "This is the first report of the potential association of increased CHST15 expression in melanoma, although the contribution of CHST15 in malignancy is increasingly recognized." (PMID 37813168, 2024). "A reduced proliferation was observed for the LCC Chst15 knock-down cells or when DS was removed from melanoma cells." (PMID 28107390, 2017). "Imaging confirms the decline in CHST15 expression in the lung melanomas." (PMID 40562100, 2025). "Different transcription factors regulate the expression of CHST11 and CHST15 in the melanoma cells." (PMID 40562100, 2025). "In normal melanocytes and B16F10 melanoma cells, similar effects of ARSB treatment on CHST15 and CHST11 expression were detected." (PMID 40562100, 2025). "Inverse to the impact of exogenous ARSB and pertinent to the development of melanoma, ARSB silencing increased CHST15 expression, abundance of C4,6S disaccharides, and activation of phospho(Tyr)-ROR1 and phospho(Ser473)-AKT1 and reduced nuclear FOXO3a and COP1 expression." (PMID 40562100, 2025).
ovarian carcinoma (4 papers, 2018 to 2023). A malignant neoplasm originating from the surface ovarian epithelium. "The same was observed previously for the chondroitin sulfate sulfotransferases CHST11 and CHST15 in ovarian cancer patients." (PMID 34201657, 2021).
colitis (2 papers, 2016 to 2022). Inflammation of the colon. "To investigate the role of CHST15 in intestinal fibrosis, we characterized the kinetics of CHST15 mRNA expression in the colon during acute and chronic experimental colitis in mice." (PMID 27410685, 2016). "Here we have used siRNA-based approach of silencing CHST15 in dextran sulfate sodium (DSS) induced colitis in mice, human colon fibroblasts and cancer cell lines." (PMID 27410685, 2016). "Thus, we initially tested whether CHST15 blockade induces delayed epithelial healing in a mouse model of acute colitis." (PMID 27410685, 2016). "CHST15 siRNA repressed intestinal fibrosis in mouse colitis surprisingly without exacerbating ulcerative lesion." (PMID 27410685, 2016).
Chronic colitis (1 paper, 2016). A chronic inflammatory disease of the large intestine (colon, cecum and rectum). "In DSS-induced chronic colitis models, CHST15 siRNA reduced CHST15 mRNA in the colon, DAI, alpha-smooth muscle actin+ fibroblasts and collagen deposition, while enhanced MH as evidenced by reduced histological and endoscopic scores." (PMID 27410685, 2016). "With this clinically applicable approach, the effect of CHST15 siRNA on chronic colitis was tested via submucosal route and with clinically-relevant parameters." (PMID 27410685, 2016). "Based on the pancolonic delivery, we next investigated the in vivo function of submucosally injected CHST15 siRNA in DSS-induced chronic colitis in mice." (PMID 27410685, 2016). "Although further investigations are needed, the simultaneous effects of both MH-induction and fibrosis-suppression found in acute and chronic colitis are attributable in part to EMT-reversing action on fibroblasts by CHST15 siRNA." (PMID 27410685, 2016). "In addition, CHST15 siRNA reduced serum IL-6 level and the excessive accumulation of macrophages that was distinct from chronic colitis." (PMID 27410685, 2016). "CHST15 siRNA significantly reduced the accumulation of fibroblasts as found in chronic colitis." (PMID 27410685, 2016).
clear cell renal cell carcinoma (1 paper, 2023). "The proliferative and metastatic capacities of cells in clear cell renal cell carcinoma are facilitated by CHST15 through the signaling pathway involving miR-125a-5p/EIF4EBP1, indicating its potential as a promising prognostic biomarker." (PMID 37812215, 2023).
colon cancer (1 paper, 2016). "Thus, CHST15 siRNA reduced EMT signaling but increased EMT-reversing properties by colon cancer cells." (PMID 27410685, 2016). "In addition, we have also measured the effect of CHST15 siRNA on the expression of EMT markers such as E-cadherin, vimentin, BMP7 and Wnt3 using TGF-β-stimulated colon cancer cell line and identified a significant suppression of these markers in the CHST15 siRNA treated cells." (PMID 27410685, 2016). "Blockade of CHST15 inhibited the activation of colon fibroblasts and reversed the EMT changes by colon cancer cells in vitro." (PMID 27410685, 2016).
COVID-19 (1 paper, 2023). A disease caused by infection with severe acute respiratory syndrome coronavirus 2. "Recently, CHST11 and CHST15 overexpression in the vascular smooth muscle cells was linked to the severe lung pathology in COVID-19 patients." (PMID 37545696, 2023). "Carbohydrate sulfotransferase 11 mRNA expression was increased by 3.1 times (N = 9, P < 0.001) and CHST15 expression was 2.1 times (N = 15, P < 0.001) higher in the vascular smooth muscle cells of COVID-19 patients that had severe lung manifestations." (PMID 37545696, 2023). "They found that increased CHST11 and CHST15 activity may lead to severe lung pathology in coronavirus disease 2019 (COVID-19) patients." (PMID 37545696, 2023).
fibrosis (1 paper, 2016). the formation of excess fibrous connective tissue in an organ or tissue in a reparative or reactive process. "The results indicate that CHST15 siRNA skews host defense towards MH instead of fibrosis in chronic fibrosis phase." (PMID 27410685, 2016).
Hearing impairment (1 paper, 2013). A decreased magnitude of the sensory perception of sound. "Mice deficient in Chst15 have not been tested for hearing impairment; however, their hematopoietic phenotype has been analysed and they exhibit decreased protease activity in bone marrow-derived mast cells." (PMID 23457544, 2013).
ovarian tumours (1 paper, 2023). "The study has shown that CHST11, CHST12 and CHST15 messenger ribonucleic acid (mRNA) tissue expressions in the malignant ovarian tumours were increased compared to the expressions in the non-malignant ovarian tumours (N = 95, P < 0.05 for each gene expression)." (PMID 37545696, 2023).
ulcers (1 paper, 2016). "We hypothesized that CHST15 and its product CS-E play a pivotal role in creating a local fibrotic field around injured sites such as ulcers and investigated the balance between MH response and fibrosis in the colon." (PMID 27410685, 2016). "Taken together with the endoscopic and histological findings, these data suggested that CHST15 mRNA is inducible in response to tissue damage and shows high levels of expression when endoscopically active ulcers accompanied by marked accumulation of macrophages and fibroblasts are evident (day 9)." (PMID 27410685, 2016).
tumor (9 papers, 2015 to 2024). "In contrast, a clear loss of CHST15 staining in the tumor regions of the CHST15 siRNA group was revealed." (PMID 26642349, 2015). "Reduced CHST15 protein signals associated with tumor necrosis were observed with the treatment with CHST15 siRNA." (PMID 26642349, 2015). "Additionally, these studies suggest that CHST15 can promote tumor progression by driving the proliferation and invasion of cancer cells, suggesting that high CHST15 might be associated with poor prognosis." (PMID 34922539, 2021). "The specific effects of decline in CSPG4 and CHST15 on the interactions of tumor cells with neighboring cells, inflammatory cells, and the extracellular matrix require further evaluation." (PMID 37813168, 2024). "carbohydrate sulfotransferase 15 (CHST15) is a specific enzyme that biosynthesizes Chondroitin sulfate E (CS-E), a highly sulfated glycosaminoglycan promoting tumor invasion and metastasis." (PMID 34445617, 2021). "Orthotropic xenograft models will provide further information on the role of CHST15 siRNA in tumor cell proliferation in a tumor microenvironment." (PMID 26642349, 2015). "In the center of tumor, the expression of CHST15 was relatively lower compared to the invasive front." (PMID 26642349, 2015). "First, we used only PANC-1 cells in vivo although, we used three different cell lines in vitro and observed similar effects of CHST15 siRNA in tumor cell proliferation." (PMID 26642349, 2015). "We also tested the effect of CHST15 siRNA on tumor growth by intratumoral injection in a xenograft model." (PMID 26642349, 2015). "After establishing the tumor, a single injection of CHST15 siRNA significantly suppressed further tumor growth." (PMID 26642349, 2015). "Second, we used a skin xenograft model to simply examine the effect of CHST15 siRNA on the proliferation and growth of tumor cells." (PMID 26642349, 2015). "In contrast, histological examination of the xenograft clearly showed the reduction of human CHST15 protein-positive tumor cells by CHST15 siRNA one week after the single injection, indicating that successful inhibition of CHST15 was obtained." (PMID 26642349, 2015). "It is possible that a decline in abundance of CSPG4 and CHST15 by treatment with exogenous ARSB may improve recognition of the tumor cells by infiltrating immune cells or may enhance contact inhibition." (PMID 37813168, 2024). "Moreover, CHST15, by sponging miR-155 and miR-194, promotes the expression of PD-L1 on tumoral cells, thus contributing to immune escape during tumour progression." (PMID 39698297, 2023). "The results of this study demonstrate the ability of locally administered, EUS-directed RNA oligonucleotides to suppress tumoral CHST15 expression, thereby increasing the population of tumor-infiltrating T lymphocytes and ultimately optimizing patient prognosis." (PMID 37444534, 2023). "Furthermore, the circRNA CHST15 has been described to act as an oncogene in lung cancer since its down-modulation correlates with reduced tumour growth." (PMID 39698297, 2023). "CHST15 was highly expressed by tumor cells located in the invasive front." (PMID 26642349, 2015). "In this study, to clarify the direct role of CS-E in tumor, but not stromal, cells of PDAC, we focused on carbohydrate sulfotransferase 15 (CHST15), a specific enzyme that biosynthesizes CS-E, and investigated the effects of the CHST15 siRNA on tumor cell proliferation in vitro and growth in vivo." (PMID 26642349, 2015). "One possible explanation for the mRNA-protein imbalance is that the level of tumor-derived human CHST15 mRNA reached a peak at earlier time points and decreased thereafter to day 9, after which the efficacy on mRNA could not be detected sufficiently." (PMID 26642349, 2015). "The present study showed, for the first time, that CHST15 siRNA could suppress tumor growth, which is considered as a primary stage of tumor progression at the primary site." (PMID 26642349, 2015).
tumor (continued). "Once the initiation of tumor growth was suppressed by the CHST15 siRNA, and, subsequently, the production of CHST15 protein was inhibited, further growth signals provided by CHST15-mediated growth factors might have been effectively suppressed." (PMID 26642349, 2015). "Thus, CHST15-CS-E axis-mediated tumor cell proliferation could be a novel therapeutic target in the early stage of PDAC progression." (PMID 26642349, 2015). "In the tumor tissues, mRNA expression of CSPG4 and CHST15 declined following treatment with exogenous ARSB (p < 0.001, two-sample t-test, two-tailed, unequal variance, n = 6)." (PMID 37813168, 2024). "In a subcutaneous xenograft tumor model of PANC-1 in nude mice, a single intratumoral injection of CHST15 siRNA almost completely suppressed tumor growth." (PMID 26642349, 2015). "Because CHST15-highly expressed tumor cells can only be detected in the invasive front, but not in the center of xenograft, it is considered that in vivo CHST15 siRNA mainly acts on these tumor cells located in the invasive front." (PMID 26642349, 2015).
cancer (7 papers, 2015 to 2024). A tumor composed of atypical neoplastic, often pleomorphic cells that invade other tissues. "CHST15 expression is unfavorable in most human cancers, underlining the relevance of this chicken in vivo model to identify new targets relevant in human pathologies." (PMID 34445617, 2021). "Carbohydrate sulfotransferases, such as CHST7, CHST11-13, or CHST15, have been suggested to be relevant in developing and progressing multiple types of cancer, as in PDA." (PMID 39098880, 2024). "It has been shown that CHST3, CHST7, CHST11-13 and CHST15 have functional relevance and prognostic potential in various cancer types." (PMID 37545696, 2023). "High CHST15 expression in the cancer stroma led to worse overall survival as compared to low CHST15 expression associated with the higher incidence of immature fibrosis (N = 64, P = 0.02)." (PMID 37545696, 2023). "Conversely, the circRNAs encoded by CHST15, WDR37, and SOX13, and their role in cancer have been previously delineated in the literature." (PMID 37106694, 2023). "Further investigation is needed to understand the CHST15-mediated mechanisms regulating cancer cell proliferation related to the p21 pathway." (PMID 26642349, 2015). "The study results revealed that there was significantly higher mRNA expression of CHST11, CHST12, CHST15 and CHST13 compared to non-malignant tumours." (PMID 37545696, 2023). "Among these, AKAP12 and ZNF483 emerged as the most differentially down-regulated coding circRNAs whereas AFTPH, CHST15 and WDR37 were differentially up-regulated in the pan-cancer RNA-Seq dataset." (PMID 37106694, 2023). "For example, study of normal and malignant human stromal cells and prostate epithelial suggested that CHST15 overexpression leads to non-canonical wingless/int-1 (WNT) signalling activation, a characteristic hallmark of cancer." (PMID 37545696, 2023).
inflammation (1 paper, 2024). Aberrant reaction of the microcirculation characterized by movement of fluid and leukocytes from the blood into extravascular tissues. "In the mouse model of carrageenan-induced systemic inflammation, increases in phospho-p38 MAPK and expression of CHST15 and CHST11 and declines in DNA-E2F binding and ARSB expression occurred in the lung, similar to the observed effects in this SPRBD model of COVID-19 infection." (PMID 38355690, 2024).
CHST15 also shares sentences with these, for which no sentence is quoted: Crohn disease (2 papers); acute myeloid leukemia (1); cardiovascular diseases (1); chondrodysplasia (1); colon adenocarcinoma (1); erythroleukemia (1); esophageal cancer (1); esophageal squamous cell carcinoma (1); glioblastoma (1); glioma (1); gout (1); hypopharyngeal cancer (1); lung (1); lung adenocarcinoma (1); lung carcinoma (1); lung disease (1); pulmonary fibrosis (1); rectum adenocarcinoma (1); renal carcinoma (1); skeletal dysplasia (1).